ENSG00000238901
Synonyms: LOC124902081
Gene: Small nucleolar RNA gene on chromosome 8 (122,671,291 to 122,671,394, forward strand). Ensembl gene ENSG00000238901.
Gene Ontology:
Biological process: RNA processing
Cellular component: nucleolus
Homologues: Paralogues in human: SNORD13D (83% identical), SNORD13 (81% identical), SNORD13P3 (80% identical), SNORD13P1 (79% identical), SNORD13E (78% identical).